NOTCH1 (notch receptor 1)
Diseases named in the same sentence as NOTCH1 in open-access papers (continued):
Sharing a sentence is not in itself a finding about the gene and the disease.
cancer (continued). "In previous studies by our group and other experts, the activation of neurogenic locus notch homolog protein 1 (Notch1) signaling was found to play a vital role in the proliferation of residual carcinoma cells." (PMID 36212390, 2022). "Curcumin in combination with piperine inactivates Notch by decreasing Notch 1 expression, thus reducing mammosphere formation in cancer." (PMID 35052553, 2021). "ADAM10 also increases the migration potential of cancer cells through the Notch 1 signaling pathway." (PMID 34298782, 2021). "Numerous studies have demonstrated that aberrant overexpression of EMT-inducing genes, such as Twist1, Snail1, Snail2, Zeb1, Zeb2, N-cadherin, and the master stemness gene Notch1, triggers cell de-differentiation and cancer stem cell genesis." (PMID 34922602, 2021). "In the case of Notch1‐driven T‐ALL, very little has been described regarding the participation of glutamine in Notch1‐mediated T‐cell malignant transformation or even in other types of cancer." (PMID 33314742, 2021). "In contrast, the existence of cases that show amplification and overexpression of NOTCH1 or 2 is supported by genome-wide expression and copy number variation studies (TCGA, The Cancer Genome Atlas)." (PMID 34944837, 2021). "NOTCH1 is a transmembrane receptor involved in different cancer hallmarks like differentiation, proliferation, metastasis, apoptosis, and chemoresistance." (PMID 34944992, 2021). "Here the authors show that Notch1 activates transcription of DNA replication factor RCF4 and that RCF4 binds and stabilises Notch1 intracellular domain (NICD1) to promote cancer metastasis." (PMID 33976158, 2021). "The expression of tumor suppressor genes, such as Cdkn2a and Notch1, was downregulated in stem-like cancer cells compared to control stem-like cells." (PMID 34785704, 2021). "This clearly explains why FBXW7 mutations or deletions promote late-stage HNSCC progression and growth as well as directly argue for a role of NOTCH1-pathway activities in this cancer entity." (PMID 34944837, 2021). "Our results provide another link between downregulated Notch1 signaling and cancer cells with diminished TET2 function and suggest a therapeutic potential of Notch receptor agonists in this setting." (PMID 34622806, 2021). "Like before, it also seemed that the expression of NOTCH1 was tissue-specific and depended on the type of cancer." (PMID 33917330, 2021). "We found that macrophage contact is unable to induce stemness in Notch1 signaling defective cancer cells." (PMID 34911937, 2021). "By lowering MSI1 expression in spheroid culture, cancer stem cell proliferation is inhibited, as is the expression of Notch1 and cancer stem cell markers such as Oct4, Sox2, and c-Myc." (PMID 34587981, 2021). "Aberrant expression of Notch-1 signaling has been reported in various types of cancers and has been correlated with cancer cell proliferation, survival, apoptosis, and differentiation." (PMID 34671398, 2021). "(ii) NF1 and NOTCH1 neoantigens represent potential therapeutic targets for immunotherapy in hypermutated cancers." (PMID 34503126, 2021). "We also demonstrated additive type of pharmacological interactions between CDDP and SAHA or VPA at the fixed-ratio combination of 1:1 in TNBC cancer cell lines with increased or decreased Notch1 activity." (PMID 34068438, 2021). "Along with the initial bioinformatic results, data from these MCF7 and HEPG2 cancer cells further confirmed downregulation of Notch1 by selenite." (PMID 33802299, 2021). "In conclusion, the transient disruption of SERCA activity can be leveraged for targeting Notch1 in cancers." (PMID 33407740, 2021).
cancer (continued). "Analysis of 233 primary and 40 recurrent HNSCC cancer biopsies revealed that high DCLK1 expression was associated with poor prognosis and showed a trend towards higher active NOTCH1 expression in tumors with elevated DCLK1." (PMID 34336664, 2021). "This was accompanied by inhibition of EMT and downregulation of EMT-modulating factor Notch1, β-catenin activity and the cancer stem cell marker Sox2." (PMID 34485294, 2021). "Curcumin also down-regulates Notch1 expression and its downstream signaling molecules in different types of cancer cells." (PMID 35052553, 2021). "It has been validated that NOTCH1 can influence proliferation, apoptosis and differentiation of various cancers." (PMID 33237585, 2021). "Although glutamine addiction has been reported in many cancer types, to the best of our knowledge this is the first time that glutamine addiction has been reported as a consequence of Notch1 activation in T‐ALL." (PMID 33314742, 2021). "SERCA inhibition hijacks Notch1 trafficking and its activation emerging as a druggable approach for NOTCH1-dependent cancers." (PMID 33407740, 2021). "The results have shown that the mutations in NOTCH1 are associated with decreased expression of the Epi1/2 programs but elevated expression of the Mes program in epithelial cells, indicating that the mutations may impair the differentiation of epithelial cells, a well-known hallmark of cancer." (PMID 34489433, 2021). "NOTCH1 is the most widely studied and characteristic member of the NOTCH receptor family due to its high mutation rate in human cancers." (PMID 34341330, 2021). "The DLL4/Notch1/Akt pathway is principally related to angiogenesis because it regulates the proliferation and migration of ECs in both normal conditions and in malignancies." (PMID 34671243, 2021). "In this context, γ-secretase inhibitors (GSIs) are the most widely studied anti-NOTCH1 molecules in cancer." (PMID 33479306, 2021). "As Notch 1 is involved in different cancers, GSIs have been proposed as a potential drug for different solid tumors and T-ALL." (PMID 33374160, 2020). "To explore the mechanisms underlying the role of miR-137 in CRC, we searched the putative targets for miR-137 using TargetScan, a miRNA target analyzing database, and found Notch1, which are known to be involved in cancer, as miR-137 targets." (PMID 33046983, 2020). "We then analyzed by RT-qPCR the expression of the different markers involved in the cancer stem cells’ biology (Sox2, Oct3/4, Notch1, Nanog, Abcg2, Aldh1a1 and Aldh1a3)." (PMID 32610610, 2020). "The best characterised member of this family is NOTCH1, which regulates the expression of key genes in cell growth and angiogenesis, playing an essential role in cancer development." (PMID 31605148, 2020). "Several investigators have found that NOTCH1 expression and activation correlate with the expression of cancer stem cell markers, including SOX2 and aldehyde dehydrogenase (ALDH) activity measured by the ALDEFLUOR assay." (PMID 33322834, 2020). "In a follow-up study, direct evidence to such a scenario was revealed in motility-related aspects, when the authors have shown that Notch1-induced invasion of the cancer cells depended on NF-κB activation." (PMID 32605277, 2020). "The very first link of the role of Notch in cancer was derived from the identification of an activating mutation in T-ALL patients, and it was linked to a chromosomal translocation of the Notch1 gene." (PMID 32796631, 2020). "Given the involvement of Notch upregulation and human cancer, we investigated the expression on the protein level of Notch1 and processing proteins." (PMID 32046305, 2020). "Altogether, these results indicate a new role of DYRK2 in cancer cell migration/invasion through the regulation of Notch1-IC levels." (PMID 31605148, 2020).
cancer (continued). "The use of Notch1 SiRNA in combination with prevalent chemotherapeutic options has consistently been shown to be a better treatment option for different cancers." (PMID 32630477, 2020). "The complex role of NOTCH1 activation in the tumorigenesis and phenotypic behavior of HNSCC would likely confound therapeutic strategies proposed to inhibit NOTCH1 signaling in this cancer type." (PMID 33322834, 2020). "In an orthotopic model of skin SCC, genetic or pharmacological inhibition of NOTCH1 activity suppresses cancer/stromal cells expansion." (PMID 33046701, 2020). "Suppression of the Notch1 signalling pathway is considered to be a novel target for human cancer treatment." (PMID 32423385, 2020). "NOTCH1, the best characterised member of this family, regulates the expression of key genes in cell growth and angiogenesis, playing an essential role in cancer development." (PMID 31605148, 2020). "Ubiquitin-proteasome-mediated degradation of NOTCH1 is a pivotal mechanism for NOTCH1 degradation in cancer cells." (PMID 32792479, 2020). "We show that DYRK2 regulation by chemotherapeutic agents has a relevant effect on the viability, motility and invasion capacity of cancer cells expressing NOTCH1." (PMID 31605148, 2020). "By reduction of MSI1 expression in spheroid culture, proliferation of cancer stem cells decreases through reduction of Notch1 and cancer stem cell markers such as Oct4, Sox2, and c-Myc." (PMID 32448364, 2020). "Recent studies suggest that compared to other Notch receptors, Notch1 activation is responsible for the aggressive induction of phenotypic and functional changes in cancer cells consistent with mesenchymal transformation." (PMID 32630477, 2020). "Even the Notch1 ligand Jagged-1 has been frequently reported to be involved in metastasis in prostate, breast, and colon cancers and the activation of NOTCH1 signaling has been shown to directly contribute to cancer cell stemness and invasion in these cancers." (PMID 32630477, 2020). "Recent studies have shown that c-Myc promotes cancer development by acting as a target of Notch1 to establish a Notch1-c-Myc pathway." (PMID 33051403, 2020). "Notch pathway inhibitors, including γ-secretase inhibitor, Notch 1 siRNA, and monoclonal antibodies against Notch receptors and ligands, are currently in clinical trials for numerous cancers." (PMID 32899791, 2020). "Here we show that NOTCH1 gene amplification and increased expression in CAFs are an attractive target for stroma-focused anti-cancer intervention." (PMID 33046701, 2020). "In many cancers, small molecules and neutralizing antibodies had been developed for targeting Notch signaling, such as γ-secretase inhibitors and antibodies for Notch 1–4." (PMID 33425722, 2020). "NOTCH1 signaling is one of the main pathways involved in cell differentiation, and this gene is frequently dysregulated in cancer." (PMID 32183222, 2020). "It is known that the activation of Notch1 contributes to the radioresistance in several cancer types." (PMID 32545442, 2020). "NOTCH1 is the most extensively studied and characterized NOTCH family member because its mutation prevalence among human cancers is higher than that for other members." (PMID 33322834, 2020). "Notch homolog 1 (NOTCH-1) plays critical roles in cancer development by inducing epithelial-mesenchymal transition, promoting cell stemness and enhancing cell invasion." (PMID 32349744, 2020). "NOTCH1 is an important factor involved in epithelial-mesenchymal transition, which is believed to be an initial step in the process of forming cancer metastasis, as well as a mechanism responsible for stem cell properties." (PMID 32733958, 2020).
cancer (continued). "As a histone methyltransferase, G9a increases the malignant behavior of cancer cells via Notch1 overexpression." (PMID 32380783, 2020). "The first reported Notch alteration in cancer was a chromosomal translocation of the 3′ region of Notch 1 into the T cell receptor β (TCR-β) locus resulting in a constitutively active Notch 1 in T cell lymphoblastic leukaemia (T-ALL)." (PMID 32575680, 2020). "Dramatic reductions in miR-34a expression were observed in all cancer models, corroborating the bond between miR-34a and both NOTCH1 and WNT deregulation, two major pathways in CRC and colorectal CSC of various origin." (PMID 32010426, 2020). "Both mechanisms are interrupted by genetic or pharmacological inhibition of NOTCH1 activation in CAFs, thereby accounting for suppression of cancer/stromal cell expansion." (PMID 33046701, 2020). "It is of interest to document the molecular docking analysis of phytocompounds from Andrographis paniculata binding with protein NOTCH1 in the Notch-signaling pathway in the context of cancer." (PMID 34803268, 2020). "Sustained NOTCH1 expression is required for CAFs proliferation and expansion and provides a target of translational significance of stroma-focused anti-cancer intervention." (PMID 33046701, 2020). "Notch1 is a well-known pathway associated with stemness phenotype in cancer, and c-Myc can bind with NOTCH1 to promote the development of cancer by acting as a target of NOTCH1 to form a NOTCH1/c-Myc pathway." (PMID 31395064, 2019). "In this study, it was demonstrated that the presence of a C-terminal mutation in the NOTCH-1 gene confers a gain of function, increasing the receptor signalling transduction in NSCLC cancer." (PMID 31443481, 2019). "Elevated Notch1 expression has been observed in a series of malignancies including HCC and is commonly associated with aggressive cancer phenotypes." (PMID 30909929, 2019). "An involvement of NOTCH1 in human cancers was first demonstrated through the discovery of translocations in T cell leukemias." (PMID 31191362, 2019). "In contrast, the decreased activity of Notch1 in the cancer cells resulted in additivity with a tendency towards antagonism, which means that a high dose of two-drug mixture is required to reach the same effect (50% inhibition of proliferation)." (PMID 31357442, 2019). "Its anti-cancer effects are carried out through degradation of several target onco-proteins, including c-Jun, Notch1, c-Myc, and cyclin E. Therefore, cellular regulation of Fbxw7 is an important step in maintaining cellular homeostasis." (PMID 31371703, 2019). "It seems that, due to the expression of Notch1 activity in cancer cells, we should individually create the treatment for the specific patient." (PMID 31357442, 2019). "Clinical impact of de-regulated Notch-1 and Notch-3 in the development and progression of HPV-associated different histological subtypes of precancerous and cancerous lesions of human uterine cervix was studied." (PMID 31417656, 2019). "NOTCH1 signaling is known to promote the survival and proliferation of cancer cells, which is potentiated by hypoxia through stabilization of the active form of NOTCH1 by HIF-1α." (PMID 31319505, 2019). "Last, a third receptor gene, NOTCH1, is the target of miR-9-5p and miR-296-5p, the two enriched miRNAs in Module 2 with involvement in AD and cancer." (PMID 31608105, 2019). "Her2 overexpression is associated with an increased subpopulation of cancer stem cells and correlates with activation of the PI3K/AKT pathway, leading to increased expression of stem cell markers Oct3/4, Notch1, Notch2, Jagged1 and Gli1." (PMID 31608299, 2019).
cancer (continued). "In benign MECs, Notch-1 activation triggers downregulation of LAMC2 resulting in cellular responses towards cancer hallmarks, including cell migration." (PMID 31848385, 2019). "It has also been shown that curcumin inhibits the expression of Notch-1-specific microRNAs including miR-21and miR-34a and upregulates the cancer suppressor let-7a miRNA." (PMID 31915510, 2019). "Many reports have shown that c-Myc binds with NOTCH1 to promote the development of cancer by acting as a target of NOTCH1 to form a NOTCH1-MYC pathway." (PMID 31395064, 2019). "Blocking antibodies against Dll4, Notch1, Notch2, or Notch3 are already being tested in phase I clinical trials in cancer patients." (PMID 31191522, 2019). "Known cancer drivers NOTCH1, PPP6C, RAC1, EIF4G1, PIK3CA showed significant increase in frequency of SCNA in transition from PPOLs to HNSCC that correlated with their expression." (PMID 31427592, 2019). "Apart from the process of cancer genesis, as one of the four main proteins of the Notch family, Notch1 signaling plays an important role in cancer development." (PMID 30622441, 2019). "As expected, the expression of NOTCH1 was significantly up-regulated in NSCLC tissues compared with para-carcinoma tissues." (PMID 31170211, 2019). "In turn, Notch1 regulates MenaINV expression, which is required for the formation of invadopodia, matrix degrading protrusions used by cancer cells for invasion, and transendothelial migration." (PMID 30200242, 2018). "The roles of Plac1 in the progression of cancers have been directly ascribed to its processing activity that gives rise to the activation of cancer‐related signal pathway proteins‐Notch1 pathway." (PMID 29704427, 2018). "Because JAG1 and Notch-1 are poor prognostic factors in several cancers, it is reasonable to propose that the role of CEA in cancer progression is mediated through JAG1 and Notch-1 expressions in M0 cells." (PMID 29580202, 2018). "It has been shown in several malignancies that there is a complex crosstalk between NOTCH1 and the transcription factor nuclear factor-kappa B (NF-κB), another key pathway involved in cancer and in CLL pathogenesis." (PMID 29998084, 2018). "Cancer pathway gene arrays followed by validation experiments identified Notch1 and Osteopontin (Spp1) to be differentially regulated by Tg6F in both the intestine and lung." (PMID 29899427, 2018). "Together, these data demonstrate that an anti-correlation between HMGA1 expression and NOTCH1 activity is evident in cancer and that this correlation can be prognostic of patient outcome." (PMID 29743479, 2018). "The expression of miR-34a was then analysed, because this miRNA has a cross talk expression regulation with c-MYC and NOTCH1 and is often down-regulated in cancer stem cells." (PMID 30218041, 2018). "The relationship between STAT3 and Notch1 signaling pathway has been reported in multiply kinds of cancer, either coordination or interaction." (PMID 29872398, 2018). "NOTCH1 staining was mainly localized at the membrane of cancer cells and in some cases limited to an apical localization." (PMID 30158530, 2018). "A variety of approaches was used to inhibit NOTCH1 for cancer therapy, including presenilin γ-secretasi inhibtors, trafficking modulators, and blocking antibodies." (PMID 29732315, 2018). "The results we present herein indicate that this pathway is not exclusive to the models we originally studied, and has broader relevance to other cancers where Notch1 and NF-κB are active." (PMID 30564555, 2018). "Motility of cancer cells can also be enhanced upon physical interaction with TAMs, which induce both RhoA activity and Notch1 signaling in tumor cells." (PMID 30200242, 2018).